EGFR (epidermal growth factor receptor)
Diseases named in the same sentence as EGFR in open-access papers (continued):
Sharing a sentence is not in itself a finding about the gene and the disease.
tumor (continued). "They reported significant association of EGFR expression with grade and tumor stage." (PMID 29879970, 2018). "Furthermore, high EGFR expression was identified to be associated with more aggressive disease, advanced tumor stage and increased risk of metastases." (PMID 29719621, 2018). "In this study we developed a novel, modular platform utilizing human IgG1 for generation of multivalent single-chain derivatives of the apoptosis-inducing TNF homology domain of TRAIL in combination with targeting of tumour-associated antigens, here demonstrated for EGFR." (PMID 29773864, 2018). "Another study found that EGFR mutation and Met activation were observed in tumor cells." (PMID 29455668, 2018). "The biopsy samples might be the only tumor material available for testing the EGFR mutation status in some cases, but these samples are often composed of variable ratios of tumor to normal cells." (PMID 30235778, 2018). "Therefore, in the present study, we studied the association of EGFR over-expression with unfavorable prognostic features including advanced tumor grade, tumor size, nodal metastasis, and recurrence status in our population." (PMID 29954411, 2018). "The most commonly used EGFR mutation testing method for the tumor tissue samples was the QIAGEN therascreen® EGFR RGQ PCR kit (QIAGEN, Manchester, UK; n = 76; 52.1%) followed by the Roche cobas® EGFR Mutation Test (Roche Molecular Diagnostics, Pleasanton, CA; n = 41; 28.1%)." (PMID 29623586, 2018). "KRAS and EGFR mutations were detected in samples with a minimum of 32% viable tumor cells." (PMID 29673125, 2018). "After treatment with available EGFR targeted therapies, a tumor could potentially harbor three co-mutations within EGFR: a driver, T790M, and third-generation TKI resistance mutation, which has therapeutic and drug development implications." (PMID 30481207, 2018). "Though EGFR mutation may be studied on tumor resection or on tumor recurrence, most of the tumors were checked for EGFR mutation at initial diagnosis." (PMID 29447182, 2018). "In early stage lung cancer patients (stages IA–IIIA), it was shown that deep sequencing for ctDNA resulted in a low sensitivity of 36.5% in detecting the EGFR (L858R) mutation present in the tumor tissue, whereas this increased to 72.7% in metastatic setting (stages IIIB–IV)." (PMID 30364656, 2018). "In the EGFR mutation, the ORRs were 62.5%, 6.7% and 34.8%(P = 0.013) in the EGFR wild type and EGFR unknown tumor subgroup." (PMID 29515799, 2018). "A higher PD-L1 expression in EGFR-mutated tumors may alter the tumor immune microenvironment, thereby promoting tumors with a more aggressive phenotype and consequently resulting in poor prognosis." (PMID 29435131, 2018). "Tumor testing for mutations in the epidermal growth factor receptor (EGFR) gene is indicated for all newly diagnosed, metastatic lung cancer patients, who may be candidates for first-line treatment with an EGFR tyrosine kinase inhibitor." (PMID 29554880, 2018). "In vivo studies have linked EGFR subcellular trafficking and chemo-resistance in many tumor types." (PMID 30413194, 2018). "Multiple EGFR mutations may be present within the same tumor which also contributes to tumor heterogeneity." (PMID 30518123, 2018). "EGFR is mutated in about 16% tumor specimens from patients with NSCLC26." (PMID 28336963, 2017). "In addition, evidence suggests that EGFR exon 19 deletion-positive NSCLC is distinct from EGFR exon 21 (L858R) point mutation-positive NSCLC with regard to the tumor response to treatment and patient survival." (PMID 28881820, 2017). "Four studies investigated on the relationship between tumor cavitation and EGFR mutation status." (PMID 28068946, 2017).
tumor (continued). "It is reported that the false positive rate is as high as 48.5% when detecting EGFR mutation in FFPE tumor tissue samples with ultra-sensitive method, especially for T790M, so no comparison between the performances of ADx-SuperARMS in tumor tissue versus in plasma was implemented." (PMID 28829813, 2017). "This study showed the different changes of EGFR mutations detected by plasma circulating tumor DNA (ctDNA) after EGFR-TKI targeted therapy which could predict the different prognosis of NSCLC patients." (PMID 28333951, 2017). "Some type of miRNAs differentially expressed in wt or mut EGFR expressing tumor tissues have been shown significant association with smoking history, and the results, however, are inconclusive among studies probably due to possible confounding effects in patient cohorts investigated." (PMID 29383112, 2017). "Interestingly, in a study of 230 surgical specimens of primary colorectal carcinoma, epithelial positive Syndecan-1 immunostaining was significantly associated with tumor size and EGFR expression." (PMID 28270211, 2017). "For patients whose tumor tissue is unavailable or inadequate, EGFR mutation detection in cfDNA with CastPCR could be first choice." (PMID 28572536, 2017). "The prognostic importance of activating KRAS mutations extends beyond predicting sensitivity to anti-EGFR monoclonal antibodies, and may reflect a more migratory and invasive tumor biology resulting in early and frequent recurrences after hepatic resection." (PMID 29108374, 2017). "Furthermore, clinicopathological variables, such as sex, tumor histology, smoking history, and tumor location, were explored in our study, and a peripheral location and smoking history were found to be associated with EGFR mutation." (PMID 28422710, 2017). "To validate whether the mutated-EGFR promotes vimentin expression, we further conducted immunohistochemistry (IHC) staining on clinical tumor samples." (PMID 28881820, 2017). "EGFR T790M mutation was found in 107 patients from tumor tissue biopsy." (PMID 29245913, 2017). "However in NSCLC, as well as in various other cancers, tumor cells do commonly express slightly mutated versions of common surface proteins, such as EGFR." (PMID 28611939, 2017). "Second, the rule of EGFR mutation detection methods in our hospital is based on the tumor purity." (PMID 29065153, 2017). "Therefore, it is imperative to explore non-invasive, convenient, and economical tumor markers as supplements to predict EGFR mutation status and to monitor EGFR-TKI treatment in NSCLC patients." (PMID 28496005, 2017). "However, low expression of both PD-L1 and CD8-positive (CD8+) tumor-infiltrating lymphocytes (TILs) in advanced EGFR-mutant NSCLC was reported to underlie the low overall response rate to PD1 inhibitors." (PMID 29296194, 2017). "It would be interesting to know whether favorable EGFR-TK mutations persisted in the tumor tissue of these individuals or whether fresh mutations, with resultant resistance to afatinib therapy, emerged." (PMID 29228636, 2017). "Moreover, the association of TRIM24 with H3K23ac is important for EGFR-stimulated cell proliferation, cell migration, colony formation, tumor growth, GSC self-renewal, p-STAT3, ID1 expression and the binding of TRIM24, H3K23ac and STAT3 with ID1 promoter." (PMID 29129908, 2017). "Recent clinical studies have shown that the primary location of the tumour may be associated with the therapeutic effects of anti-EGFR antibody treatment." (PMID 28972961, 2017). "Importantly, elevated EGFR expression was found to be associated with higher pathologic tumor stages, lymph node metastasis and higher UICC stage and with reduced overall survival." (PMID 28930282, 2017). "EGFR mutation testing is usually based on formaline fixed and paraffin embedded tumor specimens." (PMID 28949965, 2017).
tumor (continued). "This study demonstrates intra-tumoral heterogeneity of EGFR activity in a number of tumour models (breast, colorectal and lung), using an EGFR-targeted lipopolyplex to deliver DNA encoding for an EGFR biosensor, in conjunction with fluorescent lifetime imaging measurements." (PMID 28166195, 2017). "Indeed, we have shown here that a 99mTc-HYNIC-MPG radiotracer can selectively accumulate in NSCLC as a result of EGFR expressing levels and mutation status in the tumor region." (PMID 28489575, 2017). "EGFR mutation status in tumor biopsies of a cohort of 38 advanced NSCLC patients." (PMID 28854272, 2017). "The ASSESS study suggested that ctDNA use could detect EGFR mutations that may have been missed in the tumor due to use of cytology and small biopsies that can be problematic for EGFR analysis." (PMID 27980215, 2017). "Detecting EGFR mutation in cftDNA cannot totally substitute for a tumor biopsy." (PMID 28107191, 2017). "The percentage of EGFR-mutated neoplastic cells in the tumor is associated with response to TKIs." (PMID 28520821, 2017). "Besides, smoking status, tumor histology, number of brain metastasis, EGFR mutation statuses were well matched among the three groups (all P>0.05)." (PMID 29185589, 2017). "Moreover, the 49 patients who were both tumor-tissue and plasma EGFR M+ were subdivided into two groups based on the median abundance of EGFR mutations (low group: ≤ 4.15%, high group: > 4.15%)." (PMID 28052016, 2017). "Altogether, our results indicate that the NRF2 silencing-mediated miR-206 regulation could suppress BCRP levels through c-MET/EGFR modulation, providing an additional underlying molecular mechanism for the tumor sensitization by NRF2 inhibition." (PMID 29291022, 2017). "Several lines of evidence have shown that stimulation with EGF, as well as H2O2, UV, therapeutic agents, or ionizing radiation cause the EGFR to translocate to the nucleus, with nuclear EGFR signaling playing roles in cell proliferation, tumor progression, DNA repair." (PMID 28513565, 2017). "Interestingly, all three types of tumor harboring wild type EGFR or EGFR mutations showed increased PD-L1 promoter methylation and also decreased PD-L1 mRNA level after anti-PD-1 therapy." (PMID 29254184, 2017). "In this study, we reviewed 15 manuscripts to investigate whether the peripheral blood can be used as a reliable surrogate specimen for detecting EGFR mutation status in aNSCLC patients when the tumor tissue is unavailable or inadequate." (PMID 29100447, 2017). "From the present analysis, it appears that the EGFR CA repeat polymorphism may play a role synergistically with tumor EGFR expression level in predicting outcome among OSCC patients." (PMID 28694429, 2017). "We examined whether combined treatment with RT11-i and the anti-EGFR antibody cetuximab (Erbitux) could overcome cetuximab resistance in colorectal LoVo tumours harbouring the oncogenic KRasG13D mutation, using a xenograft mouse model." (PMID 28489072, 2017). "The group could show via magnetic resonance imaging and histopathology that doxycycline withdrawal or treatment with the EGFR inhibitor erlotinib caused rapid tumour regression." (PMID 28417948, 2017). "Data from multiple randomized trials have demonstrated that EGFR mutation may be used as a predictive factor for tumor response to tyrosine kinase inhibitors (TKIs) and biomarkers for TKI treatment selection." (PMID 29228994, 2017). "Furthermore, inactivation of sorting proteins, which regulate both the duration and the intensity of EGFR signaling, plays a causal role in EGFR-induced promotion of tumor growth by sustaining proliferative signaling, a hallmark of cancer." (PMID 29084952, 2017). "Moreover, emergence of BRAF mutations (V600E and G469A), which is detected in 1% of EGFR TKI-resistant tumor samples, also decreases drug sensitivity." (PMID 29140271, 2017).
tumor (continued). "This has led to its evaluation in patients with a variety of tumor types with a high prevalence of constitutive RAS signaling due to activating RAS point mutations or mutations in upstream pathway regulators such as epidermal growth factor receptor (EGFR)." (PMID 29156834, 2017). "In this study, we conducted a two-center retrospective study in EGFR mutation-positive Chinese NSCLC patients who were treated with TKIs, and evaluated the correlation of their plasma EGFR mutation profiles with changes of tumor diameter and development of new lesions." (PMID 28969034, 2017). "PET characteristics may differ when assessing cytotoxic chemotherapeutics in contrast to targeted therapies such as EGFR inhibitors depending on the mutational status of the tumor." (PMID 28102506, 2017). "The majority of BRAF mutated CRC showed high levels of active EGFR compared to other tumour types." (PMID 28282860, 2017). "Differences in associations between tumor types may be due to differential effects of growth factor stimulation with internalized EGFR." (PMID 28740577, 2017). "First, EGFR overexpressing tumour cells, high levels of STAT3 activity, loss of caveolin-1, Akt- and Myc- driven tumour cells, and argininosuccinate synthetase enzyme deficiency are all associated with a high autophagy dependency and are therefore more sensitive to CQ administration." (PMID 29225688, 2017). "This may result from underlying tumor heterogeneity and outgrowth of EGFR wildtype subclones, although we cannot exclude the possibility that other EGFR mutation types contributed to the resistance, which was beyond the detection scope of our ddPCR assays." (PMID 28969034, 2017). "In addition, the demographic, clinical and biochemical variables of patients were also evaluated for the consideration of recurrence, including age, gender, pathologic stage, tumor location, differentiation, smoking status, and EGFR mutation." (PMID 29097801, 2017). "In addition, the on-target off-tumor effect caused by CART-EGFR cells was probably the reason for the triggering of dermal toxicities due to the distribution of EGFR on the epidermis." (PMID 28057014, 2017). "We evaluated the clinical information that EGFR mutation levels in plasma samples can provide in the context of daily clinical practice, not only in terms of tumor response, but also with respect to pharmacokinetics and drug interactions and individualization of treatment." (PMID 28947971, 2017). "In the present analysis, we showed an association between tumor sidedness and gene mutations, which may explain the difference in efficacy of anti-EGFR therapy in RCRC compared with LCRC." (PMID 29212173, 2017). "The overexpression of EGFR was also associated with a poor effect of tumor radiotherapy." (PMID 28968954, 2017). "In addition to high ploidy of EGFR in the primary tumor, we also identified an activating ectodomain EGFR A289V mutation, which has been previously shown to lead to oncogenic activation and harbor sensitivity to kinase inhibitors, such as lapatinib." (PMID 28153049, 2017). "Recent studies showed the detection of clinically relevant oncologic driver mutations like e.g. KRAS, EGFR or secondary EGFR T790M resistance mutations in ctDNA with nearly maximal specificity (> 95%) compared to tumor tissue as the gold standard in cancer diagnostics." (PMID 29156792, 2017). "In addition, a greater EGFR expression in tumor rim relative to tumor center, which was found in 25% of patients, was associated with inferior survival in this patient cohort." (PMID 28456115, 2017). "The accumulation of 99mTc-HYNIC-MPG in the PC9 tumor was significantly decreased at the presence of 100 mg/Kg PD153035 and the T/M ratio was also decreased to 2.51 ± 0.30, suggesting that high uptake of 99mTc-HYNIC-MPG in the PC9 tumor is related to the EGFR-activating mutation." (PMID 28489575, 2017).
tumor (continued). "Importantly, we found that when TNBC cells are grown on Matrigel or subcutaneously injected in nude mice to form tumor, integrin αvβ3 is associated with EGFR and CL4 treatment impairs such a complex both in vitro and in vivo." (PMID 28425453, 2017). "However, small-molecule targeted inhibitors and monoclonal antibody drugs cause several adverse reactions, primarily because EGFR expression is suppressed in normal cells in addition to tumor cells." (PMID 28181832, 2017). "However, it is often difficult to obtain sufficient tumor tissues for EGFR mutation analyses from patients with advanced NSCLC who are not candidates for surgery." (PMID 28207548, 2017). "Both mutations may be needed to initiate the founder clone or an EGFR-mutated subclone that has become the dominant tumor population after acquiring the second mutation." (PMID 29228562, 2017). "Furthermore, miR-661 expression were significantly correlated with tumor size, lymph node and metastasis status instead of age, gender, smoking status, histologic type or EGFR mutation status." (PMID 28716024, 2017). "The plasma EGFR mutation abundance correlated well with tumor diameter." (PMID 28969034, 2017). "Because our study provides an EGFR mutation profile in a wider patient population, and tumour samples used in the EGFR mutation analysis were brought from hospitals in different regions of Turkey, we believe that our results reflect the EGFR mutation rate in the Turkish population more accurately." (PMID 28832323, 2017). "Greater understanding of tumor biology has since led to the discovery that tumors with sensitizing EGFR mutations, particularly the somatic mutations in EGFR exons 19 and 21, respond favorably to EGFR TKIs compared with chemotherapy." (PMID 27659294, 2017). "The recommendations for systemic anticancer therapy for stage IV NSCLC vary according to tumor histology, the patient’s performance status, and driver oncogene biomarker status, most frequently epidermal growth factor receptor (EGFR) mutation and anaplastic lymphoma kinase (ALK) translocation." (PMID 28644837, 2017). "However, all patients with common EGFR gene mutations showed expression of PD-L1 on tumor-infiltrating immune cells (2%-20% of tumor area with PD-L1 expressing immune cells in both assays)." (PMID 28969070, 2017). "Another clinical trial was also designed to study whether plasma-based EGFR mutation analysis can predict tumor response." (PMID 28099915, 2017). "Since cell proliferation was affected in most EGFR mutated cells, we hypothesized that FAM83H-AS1 affects tumor progression through the EGFR pathway." (PMID 28198463, 2017). "Subcellular localization of EGFR has been associated with outcome in a number of other tumor types." (PMID 28740577, 2017). "Therefore, we collected tumor-imaging data whenever available for all the patients whose plasma samples were EGFR mutation-positive at ≥1 post-TKI points." (PMID 28969034, 2017). "Therefore, in total, sufficient tumour sample was acquired for EGFR mutation analysis in 61/70 (87%) patients." (PMID 28367333, 2017). "To explore whether ctDNA could serve as a surrogate biomarker to monitor clinical response and emergence of resistance, we investigated the correlation between plasma EGFR mutation abundance and tumor diameter as measured by CT scans." (PMID 28969034, 2017). "Therefore, it is imperative to explore non-invasive, convenient, and economical tumor markers to predict EGFR mutation status and to monitor EGFR-TKI treatment in NSCLC patients." (PMID 28496005, 2017). "Based on these findings, it can be see that ALK and EGFR after requiring functional mutation could drive the growth of tumor cells via PI3K-AKT pathway." (PMID 29152079, 2017).